ERG (ETS transcription factor ERG)
Diseases named in the same sentence as ERG in open-access papers (continued):
Sharing a sentence is not in itself a finding about the gene and the disease.
tumor (continued). "SOX9 is a critical downstream effector of ERG in TMPRSS2-ERG-positive cancer cells and induces neoplasia and tumor invasion when overexpressed in the murine prostate or cancer cells, respectively, similarly to ERG." (PMID 35267426, 2022). "From the CNV estimation visualization, we identified significantly different CNV patterns in both ERG+ and ERG− tumor cells." (PMID 35013146, 2022). "Under short-term fasting, we observed tumor inhibition in mice bearing PGC1α silenced xenografts in comparison to ones having intact PGC1α - ERG axis." (PMID 35508713, 2022). "Clinically, individuals with ERG gene fusion are mostly documented to have advanced tumor stages, increased mortality, and higher rates of metastasis in non-surgical cohorts." (PMID 35563163, 2022). "Using immunohistochemistry, the expression levels of PACE4 isoforms in patient tissues were investigated and correlated with ERG tumor status and Gleason score." (PMID 35410344, 2022). "Prior data also showed that the percentage of ERG subtype decreases when doing a comprehensive analysis of all tumor foci." (PMID 35050902, 2022). "ERG+ tumor cells were characterized by expression of ERG and tumor markers PCA3, AMACR, and TRPM8;35–37ERG− tumor cells were marked by the expression of tumor markers PCA3 and TRPM835–37." (PMID 35013146, 2022). "Accordingly, knockdown of ERG in models of advanced PCa endogenously bearing ERG fusions reduced cell growth, cell invasion and xenograft tumor growth, arguing that advanced tumors are dependent on ERG." (PMID 35267426, 2022). "These 11 clusters included the four ERG+ tumor cell clusters we previously annotated and seven other clusters with no ERG expression which we annotated as ERG-negative (ERG-) tumor cells." (PMID 35013146, 2022). "From a therapeutic point of view, these results translate into a fine sensitivity of ERG-positive tumor cells to SPOP inhibition with a recently developed small molecule inhibitor." (PMID 35267426, 2022). "Clinically, individuals with higher ERG expression have been found to have more advanced tumor stages, elevated Gleason scores, increased mortality, and metastasis." (PMID 35563163, 2022). "When considering all tumor foci, the frequency of ERG (59.5%, P = 5.8 × 10–5) and SPINK1 (22.6%, P = 8.9 × 10–5) overexpression was significantly higher than when considering the index focus alone." (PMID 35050902, 2022). "We then asked if the elevated SPOP levels in the context of forced ΔERG expression have a functional impact on the oncogenic activity of ΔERG in the androgen-independent PC3 cells, in which ERG promotes tumor cell invasion." (PMID 33531470, 2021). "Consistent with a cell migration role for ERK/ERG target genes, GSEA of ERK ChIP signal across ERG-bound regions was enriched for the gene ontologies Ameboidal Type Cell Migration and Tumor Invasiveness." (PMID 34314419, 2021). "Similar to the clonogenic growth assay, the addition of mAKT actually decreased tumor size when combined with ERG S96E." (PMID 34314419, 2021). "Most commonly tumours possessed two subclones, however, ERG-deleted tumours tended to have a higher number (QMann–Whitney = 0.008) and KMT2A translocated lower (QMann–Whitney = 0.038)." (PMID 34753926, 2021). "For instance, we observed at least one of the Gleason pattern 4 tumours had high levels of accessibility for the ERG promoter that led to a very distinct chromatin accessibility landscape for cells from this tumour." (PMID 34911933, 2021). "The LNA anti-miRNA significantly reduced the level of miR-322 in recipient cells and reversed the effect of EVs-ERG/PTEN on tumor-sphere formation." (PMID 33500545, 2021). "Expression of exogenously expressed FLAG-tagged ERG was found to be similar in tumor samples from three mice that received vehicle treatment and three mice that received TAK-242." (PMID 33554122, 2021).
tumor (continued). "Given the various effects of ERG on the epigenome of tumor cells, we were interested in examining the interplay of miRNAs and mRNAs upon ERG overexpression in PCa." (PMID 33669024, 2021). "The results showed that the ERG status in CTC matched the status in tumor samples, both primary tumors and CRPC." (PMID 33634124, 2021). "ERG can both activate and repress the expression of direct target genes, but the relative role of these activities in tumor formation is also in question." (PMID 34314419, 2021). "While ERG has been shown to drive tumor progression and cancer-related phenotypes, as a transcription factor it is difficult to target therapeutically." (PMID 33554122, 2021). "Immunohistochemical results exhibited that the CD31, CD34, F-VIII, FLI-1, and ERG were positive in tumor cells." (PMID 34032697, 2021). "The TLR4 inhibitor, TAK-242, attenuated ERG-mediated migration, clonogenic survival, target gene activation and tumor growth." (PMID 33554122, 2021). "These proteomes showed an overlap of 489 proteins, of which 330 DEPs showed concordance in their response to up- or down-regulation of ERG protein levels, accounting for 15% of VCaP ERG proteome and 28% of LCM isolated ERG+ and ERG− tumor proteomes." (PMID 34638309, 2021). "Our findings indicate that TLR4 signaling can activate ERG transcriptional function in prostate cells via the RAS/MAPK pathway and that pharmacological inhibition of TLR4 can reduce ERG-mediated phenotypes including tumor growth." (PMID 33554122, 2021). "We also revealed tumours in which the ERG breakpoint was located before ERG, which co-existed with additional deletions and messenger RNA that incorporated intergenic cryptic exons." (PMID 34891161, 2021). "Although more patient samples and detailed further analyses of the consequences of this ERG reduction for tumour biology are required, this pilot data is an encouraging proof of principle for the use of SSOs to target ERG therapeutically in PCa." (PMID 32581342, 2020). "We found significantly lower levels for many amino acids in ERG rearrangement-positive PC samples, possibly suggesting a particularly high demand of amino acids in this tumor subtype." (PMID 32423389, 2020). "In non-tumor tissues, exosomal miR-200b-3p released from hepatocytes downregulates vascular proliferation by inhibiting ERG expression in endothelial cells." (PMID 32591615, 2020). "MiRNA-143 targets a number of tumorigenic genes including c-Myc, ERG and Ets-1 and is classed as a tumor suppressor." (PMID 31979312, 2020). "There are reports of involvement of miR-196b in the regulation of oncoproteins such as ERG and c-myc, suggesting a tumor suppressive activity." (PMID 33247705, 2020). "Given the multifocal nature of PCa, we first probed the biopsy and RP tissues for ERG expression to ensure the pre- and post-fluvastatin tissues being compared represented similar tumor foci." (PMID 32203069, 2020). "We test their effect on ERG protein expression and cancer cell biology in ERG-expressing cell lines, and their effect on tumour growth in xenografted mice and their ability to disrupt ERG expression ex vivo." (PMID 32581342, 2020). "Since LEF-1 has been related to tumor progression to metastasis and this gene has been reported to be regulated for ERG, we measured it’s expression in VCaP cells after treatment with exogenous SFRP1." (PMID 32694934, 2020). "Young PCa patients have a significantly increased tumor androgen receptor levels and positive correlation with ERG rearrangements." (PMID 32368293, 2020). "Taken together, these data suggest the E43′ SSO is stable in vivo when delivered systemically, achieving efficient knockdown of ERG to reduce tumour growth." (PMID 32581342, 2020). "To confirm that this reduced tumour growth was due to effects of the E43′ SSO on ERG splicing and protein levels within the tumour, we harvested RNA and protein from treated tumours." (PMID 32581342, 2020).
tumor (continued). "We demonstrated that SFRP1 protein increased ERG expression by promoting cellular migration in vitro and increasing tumor growth in vivo in PCa cells with the TMPRSS2-ERG fusion." (PMID 32694934, 2020). "TMPRSS2:ERG fusion status was similar across clusters, as was predominant tumor location within the prostate gland." (PMID 32599760, 2020). "Immunohistochemical staining with endothelial markers CD31, CD34, and ERG was positive for 100% of the tumor cells, and reaction with the epithelial marker PanCK was positive for 10% of the tumor cells." (PMID 33158420, 2020). "The frequency of ERG positive index tumors was 37.5% (108/288), while the frequency of positive ERG staining in any tumor focus was 54.3% (158/291)." (PMID 32341752, 2020). "Cytoplasmic expression of ACE (green) was demonstrated on the endothelium of the tumor microvessels which showed nuclear staining of ERG (red)." (PMID 33147716, 2020). "The expression of PVT1 and ERG in tumor tissues was enhanced by BMSC-EXO injection, while it was reduced by BMSC-EXOsi-PVT1 injection." (PMID 31699956, 2019). "ROCK1 up regulation was associated with androgen receptor (AR) expression, TMPRSS2:ERG fusion, genomic deletions of the PTEN tumor suppressor, as well as recurrent deletions at chromosomes 3p, 5q, 6q." (PMID 31557128, 2019). "Our data show that enzalutamide inhibited the growth of VCaP cells expressing TMPRSS2-ERG fusion genes, but when ERG factor was stably knocked down with lentiviral shERG RNA, tumor growth inhibition occurred at lesser extent." (PMID 31638934, 2019). "Treatment with EC-8042 reduced formation of tumor-spheroids from ERG/PTEN mice in vitro and impaired the re-implantation of tumor-spheroid cells in mice." (PMID 31143708, 2019). "Systemic treatment with EC-8042 inhibited tumor progression reducing invasive and proliferative areas in prostate adenocarcinomas in ERG/PTEN mice." (PMID 31143708, 2019). "ERG activation modulates the expression of more than 1,600 genes, resulting in massive changes of the molecular environment of effected tumor cells." (PMID 31452838, 2019). "Tumors from the BHP10-3SCpshCXCL16 exhibited a delayed tumor growth with decreased numbers of ERG+ endothelial cells and F4/80+ macrophages than those from the BHP10-3SCpcontrol." (PMID 31527616, 2019). "In ESR1 wild-type AI-resistant tumours ERG expression remained suppressed and was uncoupled from the recovery seen in proliferation." (PMID 30563991, 2019). "First, only a small fraction of the tumor tissue from the RP specimen was evaluated for 5hmC level and ERG expression, and the fact that PCa is known to have intratumoral heterogeneity can hamper the reliability of the biomarker status." (PMID 30818754, 2019). "Specifically, we found that EC-8042 was a potent inhibitor of tumor-sphere formation by ERG fusion positive VCaP cells, a measure of the drug's anti-CSC activity." (PMID 31143708, 2019). "Knockdown of TMPRSS2-ERG has been reported to inhibit cell proliferation in vitro, and knockdown of ERG reduced tumor progression in vivo in an orthotopic mouse model." (PMID 30664691, 2019). "While in ERG+ rearranged tumours, the earliest homozygous deletions appeared in region chr5:55-59 Mb in ERG− cancers, losses at chr5:60-100 Mb, covering the well-known affected gene CHD1, were reported." (PMID 31275657, 2019). "Strong nuclear ELAC2 expression was associated with advanced tumor stage, nodal metastasis, higher Gleason grade, presence of TMPRSS2:ERG fusion, higher Ki67-labeling index and PTEN deletion." (PMID 31452838, 2019). "We found a significant association between 5hmC level and lower age at RP (p = 0.003), lower clinical tumor-stage (p = 0.03), lower biopsy GS (p = 0.05), lower RP GS (p = 0.001) and positive ERG expression (p < 0.0001)." (PMID 30818754, 2019). "To investigate further the impact of EC-8042 on tumor-propagating stem-like cells, we took advantage of the ERG/PTEN GEM model." (PMID 31143708, 2019).
tumor (continued). "The co-association of the high ERG expression and high proliferation genes in the ESR1-mutated tumours is consistent with the tumour progression being at least partly driven by the mutations." (PMID 30563991, 2019). "Many studies reported the involvement of abnormal ectopic expression of ERG fusion proteins in many cancer types, however, limited studies reported the role of ERG in the regulation of tumor neovascularization." (PMID 31817884, 2019). "Because EndMT is known to be induced in the tumor microenvironment, we investigated the expression of ERG and FLI1 in ECs in tumor tissues by immunofluorescent staining." (PMID 30500808, 2018). "But also in prostate models due to inhibition of ERG and ETV1, YK-4-279 results in a decrease of the expression of the ERG-target genes PLAU, PLAT and ADAM10 and ETV1-target gene MMP13 associated with in vivo anti-tumor activities." (PMID 29921764, 2018). "Knockdown ofErf in mouse prostate organoids upregulates an ERG signature and, when combined withPten knockout, leads to tumor formation upon subcutaneous engraftment." (PMID 30135717, 2018). "Direct comparison between two tumor groups indicated 51 hyper-methylated sites (31 genes) in ERG-negative and 14 hyper-methylated sites (8 genes) in ERG-positive tumors." (PMID 30150711, 2018). "In the tumor microenvironment, ERG and FLI1 can be downregulated via the mixture of cytokines from many sources such as infiltrating immune cells (e.g. neutrophils, macrophages, and NK cells), ECs, CAFs, and tumor parenchyma." (PMID 30500808, 2018). "The presence of tumor vessels was confirmed by immunostaining with an anti-ERG-antibody in every case." (PMID 30680065, 2018). "In the current study, we found that soluble factors enriched in tumor tissues are responsible for reduced expression of ERG and FLI1." (PMID 30500808, 2018). "The study also yielded a similarly negative result for tumor volume, while the study by Schaefer reported that ERG overexpression was inversely correlated with the tumor size." (PMID 30459527, 2018). "Such functionally defined luminal progenitors can be transformed by distinct sets of genetic perturbations (i.e., AR+AKT/ERG or c‐MYC+PTEN knockout) to form tumor glands." (PMID 28297567, 2017). "In human PC cell lines, ERG-TMPRSS fusions have been shown to drive tumor progression through WNT signaling within the TME corresponding with immune resistance by induction of tumor tolerance in dendritic cells." (PMID 28714919, 2017). "The classification performance was similar in patient subsets based on tumor TMPRSS2:ERG fusion status." (PMID 29137428, 2017). "We confirmed ERG overexpression in PCa by comparing tumor-specific upregulated genes from three published datasets based on a 2-fold differential expression threshold." (PMID 28465491, 2017). "Identification and subsequent activation/inactivation of tumorigenic TF hubs by small molecules can impair tumor growth and development, as shown recently for ERG inhibition by dexamethasone." (PMID 28750683, 2017). "Recent studies have included PTEN, ERG and AR gene status and mRNA profiling in single circulating tumor cells." (PMID 29069718, 2017). "Quantitative evaluation of IGF-1/IGF-1R expression combined with molecular assessment of T2E status or ERG protein expression represents a useful marker for tumor progression in localized PCa." (PMID 28545426, 2017). "Confirmation of the TMPRSS2-ERG status was obtained on the tumor sample by immunohistochemistry with anti-ERG." (PMID 28055969, 2017). "Further, these alterations lead to substantial heterogeneity in tumor samples and have been used to define PCa molecular subtypes based on fusion of ETS family genes (ERG, ETV, ETV4, or FLI1) and mutations in SPOP, FOXA1, or IDH1." (PMID 28750683, 2017).
tumor (continued). "The T2E expression in each tumor was measured as reported in the Methods section and then compared to the ERG IHC status." (PMID 28545426, 2017). "Out of the six TF hub genes that are perturbed by SVs, ERG is rearranged at the highest frequency (~45% of tumor samples)." (PMID 28750683, 2017). "Errors in this process result in recombinogenic TMPRSS2:ERG fusion and eventually in clonal selection of tumor cells carrying this alteration." (PMID 27530104, 2016). "The data also suggest that presence of a 6q15 deletion including MAP3K7 - either directly or indirectly - prevents tumor cells from developing TMPRSS2:ERG fusions." (PMID 26684029, 2016). "The markedly higher fraction of intrafocal ERG heterogeneity in unifocal cancers in our study is obviously due to the particularly large size of the majority of tumor foci." (PMID 27530104, 2016). "The complete absence of focal ERG positivity in 34 cancer foci with 6q15 deletions strongly supports the concept of 6q15 deletions either directly or indirectly preventing tumor cells from developing TMPRSS2:ERG fusions." (PMID 26684029, 2016). "This gene fusion causes the oncogene ERG to be under the control of the androgen inducible TMPRSS2 promoter, which appears to have a subsequent bearing upon tumour progression." (PMID 27408704, 2016). "In a patient with ERG-rearranged tumor, 30 stacks also allowed a 95 % detection rate of CTC FISH spots." (PMID 27417942, 2016). "Although aberrantly expressed ERG fusion proteins are associated with a number of different cancers (see Section 10.3), little information exists on the role of ERG in regulating tumour neovascularization." (PMID 27208692, 2016). "A patient was considered heterogeneous for ERG immunostaining if different tumor foci had different ERG results (interfocal heterogeneity) or if at least one tumor focus showed a mixture of ERG positive and ERG negative tumor cells (intrafocal heterogeneity)." (PMID 27530104, 2016). "Other targets of SPOP include the AR and the ERG oncogene, confirming the importance of this gene in driving tumour progression." (PMID 27408704, 2016). "Tumor subtypes for the 49 tumor samples were assigned based on the DASL expression data of ERG, ETS, and SPINK1." (PMID 28027300, 2016). "To evaluate the role of ERG rearrangements with tumor progression, we next analyzed ERG heterogeneity in tumor foci of different Gleason grades." (PMID 27530104, 2016). "Within the 141 ERG-positive cancer foci, the majority (55.3 %) was homogeneously ERG positive, whereas 44.7 % showed heterogeneous staining, suggesting that ERG fusion often occurs only as a secondary event after tumor formation." (PMID 27530104, 2016). "Comparison of adjacent benign and tumor tissue revealed a significant increase in SOX9 mRNA expression in TMPRSS2:ERG fusion-positive tumors (P = 0.0012), while the expression of SOX9 in fusion-negative tumors resembled that of benign tissue (P = 0.60)." (PMID 27798103, 2016). "Fusion variants, corresponding to over-expression of ERG in the DASL data, were detected in 8 of 25 tumor samples (32%) from the older cohort and 15 of 24 tumor samples (67%) from the early cohort." (PMID 28027300, 2016). "We retrieved published miRNA expression data sets, and based on ERG expression levels, we classified the tumor samples into ERG-positive and ER-negative groups." (PMID 27191272, 2016). "miR-30 tumor suppressor has been demonstrated to connect the major EGF/Src signaling to ERG providing mechanistic insights into EMT features of ERG-positive CaP cells." (PMID 26988912, 2016). "These included 42 tumor foci with homogeneous ERG positivity and 16 with homogeneous 6q15 deletions." (PMID 26684029, 2016). "There was no major difference in the relationship between 12p deletions and tumor phenotype between ERG-positive and ERG-negative cancers." (PMID 26293672, 2015). "Results were compared to tumor phenotype, ERG status, genomic deletions of 3p, 5q, 6q and PTEN, and biochemical recurrence." (PMID 26202067, 2015).